EGFR (epidermal growth factor receptor)
Diseases named in the same sentence as EGFR in open-access papers (continued):
Sharing a sentence is not in itself a finding about the gene and the disease.
COVID-19 (continued). "Also, our findings also not only demonstrate that EGFR is a key gene in the development of critical COVID-19, but it continues to be downregulated at 12 weeks post infection even after recovery." (PMID 41141600, 2025). "BIBX 1382, an EGFR inhibitor, and paroxetine, a serotonin reuptake inhibitor, are also among the potential therapeutic agents, along with doxorubicin, which has been repurposed as an anti-COVID-19 drug." (PMID 39588145, 2024). "TGF-α, a key mediator of the EGFR pathway, was also a high-ranking driver of model prediction, suggesting that concurrent activation of pro-fibrotic epidermal growth factors are important features of severe COVID-19." (PMID 38368384, 2024). "As a result, in COVID-19, EGFR signalling may develop into a different pathway that stimulates STAT3 when lung damage occurs, and SARS-CoV-2 infection significantly reduces IFN-I production." (PMID 38628843, 2024). "TGFalpha has not been directly implicated in COVID-19, but blockade of signaling through its receptor, epidermal growth factor receptor, is linked to inhibition of SARS-CoV-2 replication." (PMID 38168138, 2024). "Additionally, our findings offer novel insights into the antiviral potential of EGFR inhibitors as promising therapeutic agents for coronavirus disease 19 (COVID-19)." (PMID 38734691, 2024). "The PPI network analysis exhibits that numerous genes, including IL-6, TNF-α, MAPK3, MAPK1, AKT1, mTOR, HIF1A, HSP90AA1, EGFR, CASP3, etc., are implicated in the pathogenicity of COVID-19 disease and also in the anti-COVID-19 effects of Meliae cortex’s key active phytonutrients." (PMID 36817449, 2023). "In addition to a more direct implication of EGFR in SARS-CoV-2 infection, some clinical associations further suggested an indirect function of EGFR for lung pathologies in COVID-19." (PMID 37402592, 2023). "At the same time, the EGFR is known to be one of the main regulators of EC cell growth, which may provide a biological rationale for targeting the EGFR in EC with high EGFR levels and comorbid COVID-19." (PMID 37239926, 2023). "A cell-cell communication analysis suggested that epidermal growth factor receptor (EGFR) signaling in epithelial cells may contribute to mild/moderate COVID-19." (PMID 37936693, 2023). "Therefore, it is of great interest to study SARS-CoV-2-infected EGFR-mutated NSCLC patients in greater depth in order to obtain a better understanding of how mACE2, sACE2, and SOC TKIs can affect the course of COVID-19." (PMID 36077610, 2022). "Besides, in COVID-19 therapy, EGFR signaling inhibitors potentiated the IFN-I response, thereby considered to be an attractive therapeutic strategy." (PMID 35847084, 2022). "The results show that Diosmetin can highly bind with novel coronavirus-specific proteins and core gene proteins, suggesting that the effect of Diosmetin on BRCA/COVID-19 may be targeted by EGFR, AKT1, and GSK3B proteins." (PMID 36060002, 2022). "Multiple pieces of evidences support the role of the EGFR in the COVID-19 pathogeny." (PMID 35937253, 2022). "We have determined that VitD regulates the EGFR gene to reduce lung infection in COVID-19 patients." (PMID 36307516, 2022). "Even in COVID-19 treatment, targeting EGFR signaling was considered to be an attractive strategy, as its inhibitors may synergistically potentiate the anti-SARS-CoV-2 activity of IFN-I." (PMID 35847084, 2022). "On the other hand, ADAM17 cellular activity has been shown to be positively regulated by epidermal growth factor receptor (EGFR) signalling, thus raising the question of the impact of anti-EGFR tyrosine kinase inhibitors (TKI) on COVID-19 susceptibility through ADAM17 down-tuning." (PMID 33531686, 2021). "In addition, a previous study screening drugs by scoring viral fibrosis based on MAPK activity indicated EGFR is a main regulator of COVID-19–related fibrosis." (PMID 34925028, 2021).
COVID-19 (continued). "Notably, EGFR has been identified as a component of the COVID-19-induced cytokine storm, and serves as a host factor in promoting viral entry, survival and propagation for SARS-CoV-2." (PMID 35153822, 2021). "It has been reported that EGFR is also a target of COVID-19 treatment." (PMID 34931923, 2021). "ELISA assays revealed higher levels of EGFR and IL-10 in COVID-19 vs. CAP patients." (PMID 35087533, 2021). "Furthermore, as indicated by the KEGG enrichment analysis, the predominant pathways enriched were Central carbon metabolism in cancer, NF-kappa B signaling pathway, Osteoclast differentiation, Coronavirus disease-COVID-19, and EGFR tyrosine kinase inhibitor resistance." (PMID 41544081, 2026). "Furthermore, certain studies suggest that drugs targeting EGFR may hold potential as treatments for COVID-19, although further research is required to explore this possibility." (PMID 38813031, 2023). "However, cancer patients receiving treatment with EGFR inhibitors had lower death rates than cancer patients receiving immunotherapy, chemotherapy or surgery, thus suggesting that EGFR inhibition has a protective effect against severe COVID-19 pathologies." (PMID 37402592, 2023). "This may open new perspectives in the treatment of COVID-19 patients by targeting EGFR." (PMID 37112680, 2023). "EGFR inhibitors are proved to have antiviral and antifibrotic effects based on the Viral Fibrotic score, indicating that EGFR may be a critical regulator of COVID-19/PF co-occurrence." (PMID 35754492, 2022). "Interestingly, primary cilia house a number of oncogenic molecules including smoothened, KRAS, epidermal growth factor receptor, and platelet-derived growth factor receptor, and thus, the role in the immune response to COVID-19 would need further investigation." (PMID 33437935, 2021). "This suggested that low levels of EGFR may be a protective factor for COVID-19." (PMID 32983259, 2020). "Hence, though the persisting downregulation of bothSHH and EGFR in critically ill COVID demonstrate common expression direction for both, additional research is needed to clarify the exact mechanism by which both genes interact in COVID-19 in tissues other than blood." (PMID 41141600, 2025). "They identified 40 intersection targets between cepharanthine and COVID-19, with key targets primarily involving Src, AKT1, EGFR, and mTOR, among others." (PMID 41303371, 2025). "The top ten anti-COVID-19 core targets, AKT1, TNF, HSP90AA1, IL-6, mTOR, EGFR, CASP3, HIF1A, MAPK3, and MAPK1, were chosen for molecular docking studies with the Meliae cortex’s key active phytonutrients determined in section 3.7." (PMID 36817449, 2023). "The top 10 of 41 potential anti-COVID-19 core targets (AKT1, TNF, HSP90AA1, IL-6, mTOR, EGFR, CASP3, HIF1A, MAPK3, and MAPK1) were identified as molecular targets of key active phytonutrients of the Meliae cortex that might be implicated in ameliorating COVID-19." (PMID 36817449, 2023). "On the other hand, eight out of ten anti-COVID-19 core targets (TNF, EGFR, CASP3, AKT1, MAPK1, MAPK3, mTOR, and IL-6) followed the human cytomegalovirus infection." (PMID 36817449, 2023). "Nine of ten anti-COVID-19 core targets (HIF1A, EGFR, CASP3, AKT1, MAPK1, MAPK3, HSP90AA1, mTOR, and IL-6) followed the pathways in cancer." (PMID 36817449, 2023). "Our study suggests the putative implication of EGFR and its related signaling pathways in SARS-CoV-2 infectivity and COVID-19 pathology." (PMID 37112680, 2023). "In conclusion, the expression of critical biogenomic markers, including the ACE2, ANPEP, EGFR, and IGF2R genes, plays a significant role in the development of mild clinical presentations in pediatric COVID-19 cases." (PMID 38813031, 2023). "The top three Meliae cortex’s key active phytonutrients were further analyzed for molecular docking with the top ten anti-COVID-19 core targets, including AKT1, TNF, HSP90AA1, IL-6, mTOR, EGFR, CASP3, HIF1A, MAPK3, and MAPK1." (PMID 36817449, 2023).
COVID-19 (continued). "The study results indicated that the expression of critical biogenomic markers, such as the first-phase (ACE2 and ANPEP) and second-phase (EGFR and IGF2R) receptor genes, was crucial in the genesis of mild clinical presentations of pediatric COVID-19." (PMID 38813031, 2023). "It is important to note that while the roles of EGFR and IGF2R in the context of COVID-19 have been investigated, their precise significance in the disease is still being explored." (PMID 38813031, 2023). "In this review, four diseases, AE of IPF, CADM, EGFR-TKI-induced lung injury, and COVID-19, which lead to rapid progressive ILD and respiratory failure, are reviewed." (PMID 36499351, 2022). "Therefore, SOC EGFR inhibitors could also alleviate COVID-19-related pulmonary fibrosis." (PMID 36077610, 2022). "Therapeutic strategies for COVID-19 patients are complex, and so the synergistic effects of BTK, FLT3, and EGFR in ALI should also be highlighted in the development of broad-spectrum antiviral compounds that boost the innate response." (PMID 36362264, 2022). "In COVID-19 patients, pulmonary fibrosis occurs mainly due to the EGFR-mediated ErbB signaling pathway producing more pro-fibrotic than anti-fibrotic effects." (PMID 36307516, 2022). "In an in vitro characterization of pulmonary fibrosis due to COVID-19, a dual antifibrotic and antiviral activity of EGFR/ErbB inhibitors has been identified in living host lung cells." (PMID 36052135, 2022). "Among the enriched significant pathways, the Coronavirus disease-COVID-19-related pathways is the most significant pathway which involved most of the hHub-DEGs notably, CXCL8, EGFR, IL6, JUN, MAPK1, STAT3, TNF, and UBA52." (PMID 36016137, 2022). "Co-targets were 194 genes intersecting with COVID-19, RA-DEGs (GSE55235), and pyroptosis-related genes, including 7 genes: CASP1, CASP8, IL1B, CASP3, JUN, EGFR, CXCL8." (PMID 36532040, 2022). "TNF, GAPDH, MAPK3, MAPK1, EGFR, CASP3, MAPK8, mTOR, IL-2, and MAPK14 are important targets for YQS in COVID-19 treatment." (PMID 35340244, 2022). "Further bioinformatic analysis revealed 8 core targets (EGFR, AR, ESR1, MAPK8, MDM2, EZH2, ERBB2 and MAPT) in the VitD-COVID-19-osteoporosis network." (PMID 36307516, 2022). "Anti-androgen treatment, anti-EGFR TKI and ICI are major therapeutic tools in cancer which, as suggested above, can impact key molecular actors of COVID-19 infectiousness." (PMID 33531686, 2021). "The EGFR and other TKRs seem to have a strong correlation with SARS-CoV-2, providing diverse insights into the treatment of COVID-19." (PMID 34063231, 2021). "Nintedanib is an EGFR inhibitor that helps prevent excessive fibrotic responses in SARS and COVID-19." (PMID 35069217, 2021). "Amygdalin is a candidate compound for COVID-19 treatment by regulating IL6, SRC, MAPK1 EGFR and VEGFA to involve in PI3K-Akt signaling pathway, VEGF signaling pathway and MAPK signaling pathway." (PMID 34908920, 2021). "Seven core targets of vitamin A against COVID-19, including CAT, EGFR, ICAM1, IL10, MAPK1, MAPK14, and PRKCB, have been detected." (PMID 34335237, 2021). "In summary, amygdalin is a candidate compound for COVID-19 treatment by regulating IL6, SRC, MAPK1, EGFR and VEGFA by way of the PI3K-Akt signalling pathway, VEGF signalling pathway and MAPK signalling pathway." (PMID 34908920, 2021). "Amygdalin is a candidate compound for COVID-19 treatment by regulating IL6, SRC, MAPK1 EGFR and VEGFA to involve in PI3K-Akt signalling pathway, VEGF signalling pathway and MAPK signalling pathway." (PMID 34908920, 2021). "Search for targets of these miRNAs, combined with plasma protein measurements, identified a differential cytokine signature between COVID-19 and CAP that included EGFR, CXCL12 and IL-10." (PMID 35087533, 2021). "In this study, we found that the core phlegm-eliminating herbs have downregulating effects on mucin (EGFR-MAPK-mucin), suggesting that it is important to use the phlegm-eliminating herbs against COVID-19." (PMID 33381519, 2020).
COVID-19 (continued). "Notably, hyperoside showed favorable predicted interactions with PI3K-Akt pathway-related targets (EGFR, PI3K, and Akt), while molecular dynamics simulations supported stable interactions with several COVID-19-related targets, including ACE2, Mpro, and RdRp." (PMID 41899484, 2026). "The interrelationship between the EGFR and IGF2R genes might impede the progression of COVID-19 from the propagating phase to the complicating phase in pediatric patients." (PMID 38813031, 2023). "Collectively, these findings suggest that both EGFR and NGAL may be critical factors in initiating and developing long-term kidney injury in COVID-19." (PMID 37626956, 2023). "The interrelationship between EGFR and IGF2R might also play a role in impeding the progression of COVID-19 from the propagating phase to the complicating phase in pediatric patients." (PMID 38813031, 2023). "In addition, cluster 1 confirms the existence of the top ten potential anti-COVID-19 core targets (AKT1, TNF, HSP90AA1, IL-6, mTOR, EGFR, CASP3, HIF1A, MAPK3, and MAPK1); consequently, the results of the PPI and cluster network analyses are congruent." (PMID 36817449, 2023). "Some genes that may be related to severe COVID-19 pathophysiology and are good candidates for experimental investigation include PRKG1, ACE, CFB, CRP, CTNNB1, EGFR, and VEGFA." (PMID 35794133, 2022). "Furthermore, STAT1 (21,435th → 32nd), STAT2, EGFR, and IRF9 (2455th → 36th) are involved in interferon signaling and have been suggested in numerous COVID-19 studies." (PMID 36291657, 2022). "This molecular docking result indicates that the physical crosstalk between COVID-19 and osteoporosis may be realized by the interaction of VitD with the core targets (EGFR and MARK8) in the ERBB and MAPK signaling pathways." (PMID 36307516, 2022). "Our results showed 13 potential targets of biochanin A; the molecular interaction network analysis using Cytoscape further highlighted the involvement of six core targets of biochanin A, EGFR, CCND1, IL2, IL1A, IL6R, and PPARG, for the treatment of CRC/COVID-19." (PMID 34931923, 2021). "Finally, IL-6, MAPK3, MAPK1, MAPK14, MAPK8, IL-1β, CCL2, EGFR, PPARG, and NOS2 were declared key targets of XFBD for COVID-19." (PMID 35185537, 2021). "In addition, IGF1R inhibitors, EGFR inhibitors, VEGFR inhibitors, and AKT inhibitors were among the compounds predicted to target COVID-19 PBMCs." (PMID 33782412, 2021). "Therefore, amygdalin is a candidate compound for COVID-19 treatment by regulating IL6, SRC, MAPK1, MAPK3, VEGFA and EGFR." (PMID 34908920, 2021). "Furthermore, seven core targets of VA against COVID-19, including MAPK1, IL10, EGFR, ICAM1, MAPK14, CAT, and PRKCB were identified." (PMID 32805728, 2020). "One case of each EGFR, ALK, ROS1, and BRAF genetic alteration were found in the COVID-19 patients." (PMID 33042826, 2020). "The analysis of COVID-19 extended interactome indicates several membrane bound gene/proteins (i.e., ICAM1, EGFR, ERBB2, APP, ADR2, FAS, CDH1, and MAPT), whose activity and/or expression could be affected by SARS-CoV-2 challenge." (PMID 33123533, 2020). "Previous research demonstrated that with increasing exposure time to SARS-CoV-2, two receptors, EGFR and IGF2R, which play crucial roles in the RAS signaling pathway, are significantly downregulated in infected human bronchial epithelial cells during the propagating phase of COVID-19." (PMID 38813031, 2023). "Moreover, EGFR inhibits IFN-I production and significantly increases during ALI, indicating that EGFR is a potential targeted pathway for treating COVID-19." (PMID 35754492, 2022). "EGFR is a very well-validated target in oncology but not in COVID-19." (PMID 35937253, 2022). "EGFR, interleukin 17 (IL-17), tumor necrosis factor (TNF), hypoxia inducible factor 1 (HIF-1), phosphoinositide 3-kinase/AKT serine/threonine kinase (PI3K/AKT) and Toll-like receptor signaling pathways were identified as the key anti-COVID-19/PF co-occurrence pathways." (PMID 35754492, 2022).
COVID-19 (continued). "Notably, EGFR was recently described as SARS-CoV-2 receptor, that supports our findings, even though these findings were independent and obtained by the study of different processes during COVID-19 infection." (PMID 34045585, 2021). "After the identification of increased EGFR expression in COVID-19 patients, induced by lung injury and STAT1 deficit, first studies now also suggest that the usage of a specific EGFR antibody could reduce inflammation and fibrosis in severe and moderate COVID-19 patients." (PMID 37402592, 2023). "The results of the current study support the hypothesis that the mild clinical presentations of pediatric COVID-19 are driven by the expression of critical biogenomic markers, specifically the first-phase receptor genes (ACE2 and ANPEP) and second-phase receptor genes (EGFR and IGF2R)." (PMID 38813031, 2023). "Thus, suppressing EGFR and CASP3 may alleviate pulmonary disease and fibrosis, as well as thrombotic events and leukopenia, respectively, which play a significant part in the pathophysiology of COVID-19." (PMID 36817449, 2023). "Investigating the impact of COVID-19 on the treatment of patients with EGFR-WT/ALK-WT mNSCLC, there was indication of delays in diagnosis during COVID-19, but with no apparent change in the tests and assessments used." (PMID 37386452, 2023). "Similarly, we observed an absence of EGFR signaling in healthy cells, and we therefore consider that EGFR inhibitors could be used as a potential treatment for mild/moderate COVID-19." (PMID 37936693, 2023). "Amphiregulin (AREG), a ligand for epidermal growth factor receptor (EGFR) not known as a major ISG in humans, is barely detectable in healthy control PBMCs but is significantly increased in COVID-19 patients’ monocytes, T cells, NK cells, and DCs." (PMID 35064122, 2022).